USP8 (ubiquitin specific peptidase 8)
Diseases named in the same sentence as USP8 in open-access papers (continued):
Sharing a sentence is not in itself a finding about the gene and the disease.
tumor (continued). "Finally, USP8 could promote tumor proliferation, invasion and stem-like properties of HCC through β-catenin." (PMID 37311739, 2023). "Herein, the results showed that USP8 levels were upregulated in clinical pancreatic tumor samples compared with those in normal tissues, meanwhile, we assessed USP8 expression in different tumor molecular and immune subtypes, attributed to the complicated subtypes in PDAC." (PMID 36539510, 2023). "Additionally, targeting newer GSC-specific markers, such as the stem-like cell marker SOX2 that promotes tumour progression or SOCS3, USP8, and DOT1L, which were recently linked to GSC growth, may be more efficient." (PMID 38136335, 2023). "The aim of the present study was to evaluate the impact of USP8 mutations on SSTR5 expression and their correlation with responsiveness to pasireotide in primary cultures from surgically removed human corticotrophs tumors and murine corticotroph tumor cells AtT-20." (PMID 35626057, 2022). "Although these results demonstrate that tumor-specific genetic depletion of USP8 could significantly enhance the therapeutic efficacy of PD-L1 blockade, the systemically using USP8 inhibitor treatment may also affect the function of other cells including immune cells in vivo." (PMID 35361799, 2022). "However, since USP8 acts on substrates that might preferentially expressed in tumors, USP8 role may in part differ between normal and tumor cells." (PMID 36578788, 2022). "Our results demonstrated that although USP8 inhibitor treatment could significantly suppress the Pd-l1-deficient CT26 tumor growth, there was no further additive effect when combined with anti-PD-L1 treatment." (PMID 35361799, 2022). "Interesting questions have arisen from these RNA sequencing studies, i.e., what is the impact of potential USP8 or GNAS driver mutations on tumor transcriptome profiles, and how does the expression of distinct PitNET cell lineage transcription factors affect other tumor lineage types." (PMID 33808624, 2021). "The four tumor samples were negative for USP8 hotspot mutations." (PMID 28533356, 2017). "Given prior studies implicating USP8 in EGFR ubiquitination, we evaluated EGFR immunoprecipitation following corticotroph tumor EGF-treatment." (PMID 40386408, 2025). "USP8 stabilizes GPX4 by suppressing its ubiquitination-dependent degradation, thereby attenuating ferroptosis sensitivity in tumor cells, driving tumorigenesis, and inducing resistance to PD-1/PD-L1 blockade." (PMID 40136465, 2025). "Stable USP8-overexpressed RM-1 cells and control cells, stable USP8-silenced RM-1 cells and control cells were subcutaneously transplanted into C57BL/6J mice and investigate the impact of USP8 expression level in tumor growth in vivo." (PMID 40410130, 2025). "However, patients with USP8 pathogenic variants had larger tumors (median tumor size: 9.5 mm [6.5, 13.3] vs. 6.0 mm [4.0, 7.0] in patients without USP8, p= 0.048), and they had higher chance of having macroadenomas (50.0%) compared to those without USP8 variants (9.4%, p= 0.039)." (PMID 40813536, 2025). "Therefore, it is possible that the USP8 P681Q mutation could impact ACTH processing or secretion in corticotroph tumor cells, without any actions on the EGFR pathway." (PMID 40544420, 2025). "When the scientists inhibited USP8 in combination with SAS, they revealed a reduction in tumor growth and high CD8+ T-cells infiltration." (PMID 41339932, 2025). "In addition, we also validated whether USP8 inhibited tumor formation in vivo." (PMID 38973004, 2024). "Studies have shown that the USP8 inhibitor DUBs-IN-2 enhances MHC-I antigen presentation, promoting CD8+ T cell-mediated tumor killing." (PMID 39223632, 2024).
tumor (continued). "USP8 inhibition in combination with PD-1/PD-L1 blockade increased CD8+ T cell infiltration and diminished tumor growth, compared to immune checkpoint blockade monotherapy." (PMID 38915093, 2024). "We identify the USP8 is a β-catenin DUB that stabilizes OGT and promotes tumor growth, invasion, though its deubiquitylation activity." (PMID 38973004, 2024). "In this case, since the tumor appeared to be a rare tumor, we used the Illumina TruSight assay up front and discovered the PDGFRA::USP8 gene fusion." (PMID 38401149, 2024). "Combining a USP8 inhibitor with PD-1/PD-L1 blockade markedly stimulates CD8+ T cell infiltration, leading to tumor suppression and improved survival in various mouse tumor models." (PMID 38638430, 2024). "Similar trends were observed in the xenograft tumor model: both PTEN and USP8 protein levels were diminished in SNHG1 overexpressed tumor tissue, and these levels showed a positive correlation." (PMID 38365726, 2024). "Therefore, the combination of USP8 inhibitor and αPD-L1 could reduce tumor migration in vivo." (PMID 36539510, 2023). "Recent cohort studies demonstrated that patients with USP8 mutant tumors had higher postoperative 24h-hour urinary-free cortisol and ACTH levels, indicating tumor recurrence." (PMID 37109772, 2023). "USP8 also is capable of directly deubiquitinating and stabilizing the type II TGF-β receptor TβRII which expressed in cell membrane and tumor-derived extracellular vesicles (TEVs)." (PMID 37658402, 2023). "In conclusion, we demonstrated that USP8 is a β-catenin DUB that stabilizes β-catenin and promotes tumor growth, invasion, tumor stem-like properties and ferroptosis resistance though its deubiquitylation activity." (PMID 37311739, 2023). "Further analysis demonstrated that pharmacological inhibition or knockout of USP8 in HCC cells triggered ferroptosis and inhibited tumor growth both in vitro and in vivo." (PMID 37867237, 2023). "To address the role of USP8 in HCC in vivo, we utilized a xenograft model to assess tumor formation in nude mice." (PMID 37311739, 2023). "USP8 also promotes epithelial-mesenchymal transition (EMT), invasion, and metastasis of tumor cells in response to TGF-β/SMAD signaling." (PMID 37311739, 2023). "However, USP8 mutation carriers generally have small tumor size, which is no more than 5 mm." (PMID 38023185, 2023). "By reducing PD-L1 and USP8 expression, lncRNA SNHG12 silencing constrained tumor progress and elevated the proportion of CD8 + T cells in NSCLC." (PMID 37658402, 2023). "Patients receiving intensive chemotherapy of their NBT showed significantly reduced tumor tissue expression of USP24, USP34, MINDY2, USP8, JOSD1, USP52, and USP12 when compared to the observation group." (PMID 37892185, 2023). "Compared with that in normal mouse pancreas tissues, IHC also demonstrated elevated expression of USP8 in KPC (KrasLSL-G12D; Trp53LSL-R172H; Pdx1-Cre) tumor tissues, which had been initially activated in PanIN1 lesions." (PMID 36539510, 2023). "Therefore, it can state that USP8 may be considered a novel target for future experiments exploring elaborate mechanisms and interactions among the upstream and downstream proteins or signaling pathways involved in tumor growth, aggressiveness, and metastasis." (PMID 36338727, 2022). "Silencing lncRNA SNHG12 restricted tumor growth and upregulated the ratio of CD8+ T cells by decreasing USP8 and PD-L1." (PMID 35658874, 2022).
tumor (continued). "Moreover, the present study provides an in vitro functional characterization of the novel G664R USP8 genetic variant firstly identified in one patient with CD and located outside the USP8 mutational hotspot and demonstrates its possible implication in ACTH-secreting tumor pathogenesis." (PMID 34439178, 2021). "A novel USP8 variant was identified in a CD patient, and in vitro functional studies in AtT-20 cells suggested that this somatic variant might be clinically relevant in ACTH-secreting tumor pathogenesis, expanding the characterization of USP8 functional domains." (PMID 34439178, 2021). "For example, USP8 may stabilize the type II TGF-β receptor, thereby enhancing TGF-SMAD axis activity and promoting tumor invasion." (PMID 41565619, 2026). "Tumor growth in the high PAAG stiffness group was significantly faster than that in the low PAAG stiffness group, and could be rescue by USP8 silencing." (PMID 40410130, 2025). "The tumor weights and volumes were increased in the high PAAG stiffness group than that in the low PAAG stiffness group, and could be rescue by USP8 silencing." (PMID 40410130, 2025). "Moreover, the anti-tumor efficacy of DUB-IN-3 combined with pemigatinib surpassed that of pemigatinib alone, suggesting that USP8 inhibition can enhance pemigatinib sensitivity." (PMID 41301681, 2025). "Moreover, several DUBs, such as USP28 and USP8, have been reported to regulate hypoxia-inducible factor proteins, the key mediators in maintaining multiple CSC populations under the hypoxic tumor microenvironment." (PMID 38517383, 2024). "In addition, USP8, USP15, USP9X, and USP18 can directly bind to PD-L1, stabilizing PD-L1 expression and promoting immune evasion by tumor cells." (PMID 39315102, 2024). "Moreover, to further confirm that CD8 + T cells were the mediators of anti-tumor immunity, we depleted CD8 + T cells prior to inoculation with KPC cells and combined USP8 inhibitor and αPD-L1 treatment." (PMID 36539510, 2023). "However, a population that showed preferential localization of USP8 in the nucleus had high ACTH production, even though the tumor sizes were small." (PMID 36834633, 2023). "We performed bioinformatic analysis of USP8 using mRNA expression data from tumor samples and paired normal tissues at the TCGA." (PMID 36539510, 2023). "Our results above suggested that USP8 regulated the efficacy of anti-PD-1/PD-L1 immunotherapy largely through two arms: the TRAF6-PD-L1 axis and the TRAF6-NF-κB-MHC-I pathway, to shape the tumor microenvironment." (PMID 35361799, 2022). "Transient cell transfection with S718del USP8 mutant in the in vitro resistant tumor (#3) did not confer pasireotide responsiveness." (PMID 35626057, 2022). "Strikingly, our results showed that combinational treatment of the USP8 inhibitor plus anti-PD-L1 antibody significantly suppressed tumor growth and improved the overall survival rates of MC38 tumor-bearing immunocompetent C57BL/6 mice compared to either single-agent or control-treated group." (PMID 35361799, 2022). "At the same time, cell transfection with S718del USP8 did not confer sensitivity to pasireotide to the in vitro resistant tumor." (PMID 35626057, 2022). "In particular, germline and somatic genome alterations (AIP, MEN1, GNAS, and USP8), dysregulated signaling pathways (Notch, Wnt, TGF-β, and cell cycle regulation), and tumor microenvironment factors were characterized, while the role of other species of RNA awaits full characterization." (PMID 33808624, 2021). "At the same time, gene expression profiles analysis in USP8 mutant and wild-type tumors revealed that counter regulatory mechanisms may fine-tune the EGFR-MAPK pathway in tumor corticotroph cells." (PMID 34439178, 2021).
tumor (continued). "Interestingly, surgical remission rates are higher in patients with USP8-mutated tumors, which may reflect these tumors are smaller and thus may suggest USP8 mutations are not a critical factor in the development of aggressive tumor behavior." (PMID 32012988, 2020). "Interestingly, in a recent multi-omics study, the silent corticotroph tumors presented low EMT, whereas USP8-wild-type functioning tumors showed and increased EMT, somehow challenging the classical imagistic phenotype of SCA as an aggressive tumor." (PMID 33066652, 2020). "ITCH and USP8 silencing experiments highlighted the role of this ubiquitination/deubiquitination process in modulating 9F7-F11-induced c-FLIP and HER3 degradation, and also in the inhibition of caspase-8-mediated apoptosis of tumor cells." (PMID 31443721, 2019). "Additionally, in vitro, the USP8 inhibitor-αPD-L1 combination therapy did not significantly improve the killing of tumor cells by activated T cells in Cd274 KO KPC cells compared to parental KPC cells." (PMID 36539510, 2023). "On the contrary, cytotoxic T lymphocytes (CTLs) play tumor-killing roles in the TME, and it is illustrated to be activated by an application of the USP8 inhibitor along with anti-PD-L1 agents because inhibition of USP8 could prevent PD-L1 from proteasome degradation." (PMID 38174069, 2023). "However, neither the genes encoding AURKA and USP8 nor those encoding USP48, BRAF, BRG1 and CABLES were affected in this tumor." (PMID 35563252, 2022). "Unfortunately, due to lack of material, we could not test the immunoreactivity of G664R USP8 in the tumor sample of the patient, thus the intracellular localization of G644R USP8 in human corticotropinomas remains to be fully demonstrated." (PMID 34439178, 2021). "However, the status of USP8 and of SSR5 receptors in the smallest tumors (close to 50%, not detectable by MRI) is largely unknown because it is difficult to obtain sufficient tumor tissue to characterize their molecular status." (PMID 31875276, 2020). "Additionally, Ubiquitin-specific peptidase 8 (USP8) inhibition markedly boosted and activated the CD8+ T cells through increasing the expression of PD-L1 in tumor cells and triggering the NF-κB pathway, thereby inhibiting tumor growth, improving the outcomes of anti-PD-L1 therapy." (PMID 40611940, 2025). "Interestingly, we observed that the animal model did not lead to liver and lung tumor metastasis, but the number of spleens with tumor migration and invasion decreased after treatment with the USP8 inhibitor and αPD-L1; however, there was no change in abdominal lymph nodes." (PMID 36539510, 2023). "In humans, the hot-spot mutations were found to result in an increased USP8 protein expression, clustering to the nucleus, that correlated in some publications with an increase in EGFR expression in the tumour tissue, while other studies could not confirm this correlation." (PMID 28005997, 2016). "However, whether targeting USP8 can enhance anti-tumor immunity has not been reported." (PMID 35361799, 2022). "On the other side, however, they are surely less prevalent than those found in the deubiquitinases USP8 and USP48, thus suggesting a more likely contribution in the modulation of tumor phenotype rather than in the transformation and/or progression." (PMID 35742910, 2022). "We observed nonsilent SNVs or indels in USP8, BSN and SLC35G5 in 1.9, 1.7 and 1.4% of tumours respectively." (PMID 34753926, 2021). "Investigated molecules without connection to common key tumor proteins are GNAS, USP8, USP48, HHIPL1, NNAT, RHOU, C5orf66 and RASSF3, which seem to be more specific biomarkers and therefore should be validated for concordant differences in liquid biopsies." (PMID 32498309, 2020). "Analysis of infiltrated immune cells demonstrated that the USP8 inhibitor combined with anti-PD-L1 treatment could significantly increase the percentage of CD8+ T cells, but not the CD4+ cells in tumor-infiltrating lymphocytes (TILs)." (PMID 35361799, 2022).
cancer (51 papers, 2017 to 2026). A tumor composed of atypical neoplastic, often pleomorphic cells that invade other tissues. "USP8 deubiquitinates numerous plasma membrane receptors, making this enzyme a promising target in cancer therapy to overcome chemoresistance associated with RTK stabilization." (PMID 39576689, 2024). "Some evidence indicated USP8 was commonly overexpressed in human malignancies and was associated with poor overall survival in cancer patients." (PMID 38973004, 2024). "Previous studies reported that Wnt/β-catenin pathway is associated with the tumorigenicity of HCC cancer stem cells, we then examined the role of USP8 in HCC stemness characteristics." (PMID 37311739, 2023). "Furthermore, previous studies have demonstrated that elevated USP8 expression is associated with a poor prognosis in various types of cancers, suggesting that USP8 contributes to tumorigenesis." (PMID 35361778, 2022). "Notably, accumulating evidence suggests that upregulated or mutated USP8 can lead to cancer progression, metastasis, and poor survival by affecting multiple signaling pathways in different types of tumors, including, but not limited to, lung, gastric, and breast cancers." (PMID 36539510, 2023). "Although our focus has been on CTLA4 expressed in cancer cell lines, we have also shown that our findings with respect to USP8 and CTLA4 translate to T cells." (PMID 39404738, 2025). "HD-PTP recruits USP8 to deubiquitylate CTLA-4 in cancer cell lines, mouse CD4-positive T cells and cancer cell-derived exosomes." (PMID 41031910, 2025). "The endosomal deubiquitylase, USP8, interacts with CTLA4, and its loss enhances CTLA4 ubiquitylation in cancer cells, mouse CD4+ T cells, and cancer cell–derived exosomes." (PMID 39404738, 2025). "USP8 is a cysteine ubiquitinase belonging to the USP family, and a large number of studies have reported on the role of USP8-mediated ubiquitination in cancer." (PMID 37783914, 2023). "And the compound DUB‐IN‐3, a small molecular inhibitor of USP8, showed the most effective anti‐cancer responses." (PMID 37867237, 2023). "Increasing evidence suggests that USP8 expression is upregulated, which stabilizes multiple oncogenes, in various cancers." (PMID 37415977, 2023). "In summary, we report that USP8 inhibition promotes ferroptosis by promoting ferritin degradation in cancer cells." (PMID 37051673, 2023). "Another attractive strategy would rely on the use of inhibitors of TGF-β signaling molecules in cancer cells, such as ubiquitin-specific peptidase 8 (USP8) which is a metastasis enhancer and an active deubiquitinase in aggressive tumors (eg. breast)." (PMID 36741364, 2022). "Among the subfamily of ubiquitin-specific peptidases, USP8 appears to be involved in modulation of cancer cell survival by still poorly understood mechanisms." (PMID 36578788, 2022). "In fact, CRISPR–Cas9 essentiality screens in cancer cells suggest that USP8 has a general relevance in cell viability as also evidenced by its physiological role, which appears non-redundant." (PMID 36578788, 2022). "To further explore the physiological function of USP8, we performed the transcriptomic analysis to comprehensively understand the signaling pathways are mainly regulated by USP8 in cancer cells." (PMID 35361799, 2022). "Taken together, our study uncovers a conserved Usp8-Tak1-JNK axis to promote tumor cell migration, and provides USP8 as a potential therapeutic target for JNK-related cancers." (PMID 35361778, 2022). "In the group of cancer patients with low USP8 expression, a higher level of CTL indicated a better survival." (PMID 35361799, 2022). "Previous studies also showed that USP8 is frequently overexpressed in human cancers and cancer patients with high USP8 expression have shown worse overall survival." (PMID 35361799, 2022).